PIEZO1P1 (piezo type mechanosensitive ion channel component 1 pseudogene 1)
Synonyms: bA164D18.1; C20orf83; FAM38CP
Gene: Processed pseudogene on chromosome 20 (59,460,619 to 59,460,837, reverse strand). Ensembl gene ENSG00000233686.
Diseases named in the same sentence as PIEZO1P1 in open-access papers:
PIEZO1P1 is named in the same sentence as 1 disease in open-access papers, as found by Europe PMC text mining. Sharing a sentence is not in itself a finding about the gene and the disease. The quoted sentences say what the papers report.
fibrosis (1 paper, 2022). the formation of excess fibrous connective tissue in an organ or tissue in a reparative or reactive process. "Consistent with the development of pathological LVH, TAC was associated with increased cardiac fibrosis (P < 0.001) and enhanced collagen III (Col3a1) expression (P < 0.001) in both WTLs and Piezo1P1-tdT/P1-tdT mice." (PMID 39195867, 2022).